PGK1 (phosphoglycerate kinase 1)
Diseases named in the same sentence as PGK1 in open-access papers (continued):
Sharing a sentence is not in itself a finding about the gene and the disease.
colitis (2 papers, 2022 to 2024). Inflammation of the colon. "In vivo, PGK1 and ALDOA silencing enhances UCB salutary effects in trinitro-benzene-sulfonic-acid-induced colitis in NOD/scid/gamma humanized mice where control over disease activity and enhanced immunoregulatory phenotypes are achieved." (PMID 36131123, 2022). "In Crohn’s disease, silencing of PGK1 and ALDOA restores Th17 cell ability to acquire an immunoregulatory phenotype in the presence of UCB and limits disease activity in a model of colitis in humanized mice." (PMID 36131123, 2022). "The effects of UCB on Pgk1 and Aldoa were also tested in mice with DSS-induced experimental colitis." (PMID 36131123, 2022). "We observed a reduced relevant abundance for hexokinase (HK1), glucose-6-phosphateisomerase (GPI), phosphofructokinase (PFKL), fructose 1,6-biphosphate aldolase enzymes (ALDOA, ALDOB), triosephosphate isomerase (TPI), phosphoglycerate kinase 1 (PGK1), and alpha enolase (ENO1) in colitis." (PMID 38668322, 2024). "Silencing of PGK1 and ALDOA restores Th17 cell response to UCB in vitro, as reflected by an increase in the expression of immunoregulatory markers like the ectoenzyme CD39; and boosts UCB immunosuppressive properties in vivo, in an experimental model of colitis in humanized mice." (PMID 36131123, 2022).
colon adenocarcinoma (2 papers, 2016 to 2021). "Next, we searched the TCGA database and found that the NRF2 (NFE2L2) gene was positively correlated with the Warburg enzymes LDHA, PGK1, and HK2 in colon adenocarcinoma." (PMID 34094899, 2021).
Crohn disease (2 papers, 2022 to 2025). A gastrointestinal disorder characterized by chronic inflammation involving all layers of the intestinal wall, noncaseating granulomas affecting the intestinal wall and regional lymph nodes, and transmural fibrosis. "Th17-cells of Crohn’s disease patients display heightened PGK1 and ALDOA and defective response to unconjugated bilirubin." (PMID 40046063, 2025). "Th17-cells of Crohn’s disease patients display heightened PGK1 and ALDOA and defective response to UCB." (PMID 36131123, 2022). "In Crohn’s disease, there was a positive correlation between the levels of PGK1 or ALDOA and Montreal type." (PMID 36131123, 2022). "Unconjugated bilirubin modulates Th17-cell metabolism in Crohn’s disease by limiting glycolysis and through downregulation of phosphoglycerate-kinase-1 (PGK1) and aldolase-A (ALDOA)." (PMID 36131123, 2022). "Among the Kegg glycolysis DEGs, PGK1 and ALDOA were the genes most significantly impacted by exposure to UCB in both controls and Crohn’s disease patients." (PMID 36131123, 2022). "Decrease in PGK1 and ALDOA mRNA levels was also noted in Th17 cells of Crohn’s disease patients although to a lesser extent than in healthy controls." (PMID 36131123, 2022). "At baseline, prior to UCB addition, PGK1 and ALDOA mRNA levels were higher in peripheral blood derived Th17 cells of Crohn’s disease patients, when compared to controls." (PMID 36131123, 2022). "PGK1 and/or ALDOA blockade might have therapeutic effects in Crohn’s disease by favoring acquisition of regulatory properties by Th17-cells along with control over their pathogenic potential." (PMID 36131123, 2022). "Therefore, blockade of PGK1 or ALDOA should be considered as a potential immunotherapeutic strategy to boost AhR activation and ultimately control Th17 cell inflammatory potential while favoring the acquisition of suppressive features by these cells in Crohn’s disease." (PMID 36131123, 2022). "Here we report that UCB controls glycolysis and downregulates glycolysis-related genes, mainly phosphoglycerate-kinase-1 (PGK1) and aldolase A (ALDOA), these effects being apparent in Th17 cells obtained from healthy individuals but not in those derived from Crohn’s disease patients." (PMID 36131123, 2022). "Importantly, exposure to UCB could reduce PGK1 and ALDOA levels in Th17 cells derived from the peripheral blood of healthy controls, after challenge with high concentration glucose; whereas such an effect was not present when considering Th17 cells derived from Crohn’s disease patients." (PMID 36131123, 2022).
diabetes (2 papers, 2022 to 2025). "Pharmacological inducers activating HIF-1, like dimethyloxalylglycine (DMOG) or deferoxamine (DFO), have been shown to partly restore the HIF-1 function in diabetes and increase the expression of phosphoglycerate kinase 1 (PGK1)." (PMID 34651203, 2022).
ductal breast carcinoma (2 papers, 2020 to 2021). "PGK1 protein has high expressions in BRCA tissues (Ductal carcinoma and Lobular carcinoma), while it has low protein expression in normal breast tissues by HPA." (PMID 34291087, 2021).
esophageal squamous cell carcinoma (2 papers, 2023 to 2025). Esophageal squamous cell carcinoma (ESCC) is a type of esophageal carcinoma (EC) that can affect any part of the esophagus, but is usually located in the upper or middle third. "Hypoxia's promotion of tumourigenicity and tumour migration ability was abrogated by PGK1 knockdown, at least in the esophageal squamous cell carcinoma setting." (PMID 40534132, 2025).
gastric adenocarcinoma (2 papers, 2006 to 2023). "In a separate study, RNA knockdown of phosphoglycerate kinase 1 (PGK1) through adenovirus-shPGK-1 was shown to reduce viability in human gastric adenocarcinoma cell lines." (PMID 37894473, 2023). "However, in the present study, a significant relation between PGK-1 protein expression and the phenotypes of gastric adenocarcinomas was hardly detected." (PMID 17187689, 2006).
glycogen storage disease (2 papers, 2012 to 2019). "In fact, PGK1 deficiency is one of the less frequent types of muscle glycogenoses or Glycogen Storage Diseases (GSD), specifically, type IX (GSD-IX), and, as such, these patients present similar clinical features to those reported in other muscle glycogen storage disorders." (PMID 31658606, 2019).
Huntington disease (2 papers, 2020 to 2021). Huntington disease (HD) is a rare neurodegenerative disorder of the central nervous system characterized by unwanted choreatic movements, behavioral and psychiatric disturbances and dementia. "Finally, based on pathway, three genes were associated with cytoskeletal regulation by Rho GTPase pathway (ACTB, PFN1 and CFL1) while two genes were associated each with glycolysis (GAPDH and PGK1) and Huntington disease (GAPDH and ACTB)." (PMID 34681026, 2021). "In contrast, decreased proteins were found in glycolysis (Eno2, Pgk1, and Tdh3), Huntington’s disease (Tdh3), isoleucine biosynthesis (Ilv5) and valine biosynthesis (Ilv5)." (PMID 31973232, 2020).
invasive breast carcinoma (2 papers, 2017 to 2021). A carcinoma that infiltrates the breast parenchyma. "In particular, quantification of the expression of EPO, ETS1, PGK1, TPI, LDHA and ENO1 in a primary tumor sample provides information on the risk of recurrence for patients with early-stage invasive breast cancer." (PMID 28430808, 2017).
invasive candidiasis (2 papers, 2022 to 2024). "In a C. albicans study, the detection of the antibody-reactivity patterns between the fungal Eno1 and Pgk1 proteins and the sera from patients with a Candida infection could differentiate patients with invasive candidiasis from those with non-invasive candidiasis." (PMID 38542504, 2024). "Furthermore, it was shown that recombinant Pgk1 antigens of C. albicans reacted to sera from patients with invasive candidiasis infected with various Candida species, including C. albicans, C. tropicalis, C. parapsilosis, C. glabrata, C. lusitaniae, C. krusei, and C. guilliermondii." (PMID 35215174, 2022).
Kawasaki disease (2 papers, 2021 to 2025). A rare inflammatory disease characterized by an acute febrile, systemic, self-limiting, medium-vessel vasculitis primarily affecting children. "In a recent study, PGK1 was used as an immune target in Kawasaki disease." (PMID 33140498, 2021). "In addition, PGK1 can be regarded as an immune target in Kawasaki disease." (PMID 40046063, 2025).
kidney cancer (2 papers, 2015 to 2022). Primary or metastatic malignant neoplasm involving the kidney. "We further assayed PGK1 expression level in pathological subgroups of the kidney cancer." (PMID 35121728, 2022). "As expected, PGK1 level between cancer and normal tissues showed significant statistical differences in totally 36 separate analyses on multiple types of cancers, among which 3 sets of kidney cancer data confirmed PGK1 in kidney tumors was higher than that in corresponding normal tissues." (PMID 35121728, 2022). "In this study, we have confirmed that PGK1 is specifically overexpressed in KIRC tissues, not in KICH or KIRP tissues, which is of great significance for the accurate diagnosis and treatment of kidney cancer." (PMID 35121728, 2022).
meningioma (2 papers, 2011 to 2025). A generally slow growing tumor attached to the dura mater. "When predicting the recurrence in WHO grade I meningiomas, PGK1 expression shows the largest effect size." (PMID 41154381, 2025). "PGK1 is included in the recently developed 34-gene expression signature for predicting meningioma recurrence and therapy response." (PMID 41154381, 2025). "The majority of grade I tumors showed low expression, whereas grade III meningiomas displayed high PGK1 expression." (PMID 41154381, 2025). "Bestkeeper-1 considered ACTB inconsistent with SD = 1.00 in meningiomas and their control tissue, whereas PGK1 was inconsistent in meningiomas (SD = 1.04)." (PMID 21806841, 2011). "Our analysis identified PGK1 expression as the most significantly correlated with meningioma grade." (PMID 41154381, 2025). "PGK1 protein was expressed in each tumor sample; however, its clear grade-related increase in expression levels was observed with the highest expression observed in anaplastic meningiomas." (PMID 41154381, 2025). "Phosphoglycerate kinase 1, a housekeeping gene, was detected in all samples; however, its protein level was markedly elevated in atypical and anaplastic meningiomas compared to benign tumors, reinforcing the notion of increased metabolic adaptation in high-grade meningiomas." (PMID 41154381, 2025). "Eight highest ranked reference genes (CASC3, EIF2B1, IPO8, MRPL19, PGK1, POP4, PPIA, and RPL37A) plus GAPDH and ACTB were then analyzed in 35 meningiomas, arachnoidea, dura mater and normal brain." (PMID 21806841, 2011).
oropharyngeal cancer (2 papers, 2022 to 2025). Carcinoma, predominantly squamous cell, arising from the epithelial cells of the oropharynx. "Proteomic mass spectrometry analysis of salivary exosomes from human papillomavirus (HPV)-driven oropharyngeal cancer patients revealed significantly elevated aldolase, glyceraldehyde dehydrogenase-3-phosphate dehydrogenase (GAPDH), LDHA/B, phosphoglycerate kinase 1 (PGK1) and PKM1/2." (PMID 36588730, 2022).
osteoporosis (2 papers, 2025). A condition of reduced bone mass, with decreased cortical thickness and a decrease in the number and size of the trabeculae of cancellous bone (but normal chemical composition), resulting in increased fracture incidence. "PGK1 emerged as a central downregulated gene in sarcopenia and osteoporosis, enriched in fibroblasts and modulated by lamivudine." (PMID 41082466, 2025). "Differential expression analysis in osteoporosis and sarcopenia datasets revealed that seven biomarkers—BCL6, DDIT4, FOXO1, IRS1, NFKBIA, PGK1, and STAT3—were differentially expressed in the independent osteoporosis dataset GSE84500." (PMID 41282482, 2025). "Results revealed significant differential expressions of DDIT4, FOXO1, NFKBIA, PGK1, and STAT3 in the osteoporosis model." (PMID 41282482, 2025).
prostate tumor (2 papers, 2020 to 2023). "Apart from these, the enhanced activation of the CXCL12/CXCR4 axis in metastatic sites instituted an angiogenic switch and promoted prostate tumor metastasis that is mediated by a decreased expression of the glycolytic phosphoglycerate kinase 1 (PGK1) enzyme." (PMID 32585812, 2020). "Therefore, Phosphoglycerate Kinase-1 (PGK1), a biomarker related to the aggressiveness of prostate tumor cells, would be downregulated by miR-143." (PMID 37191432, 2023).
retinitis pigmentosa (2 papers, 2011 to 2024). Retinitis pigmentosa (RP) is an inherited retinal dystrophy leading to progressive loss of the photoreceptors and retinal pigment epithelium and resulting in blindness usually after several decades. "For example, PGK1 (phosphoglycerate kinase) can cause a phenotype of retinitis pigmentosa and myopathy." (PMID 38892829, 2024). "In the retina, PGK1 appears to be upregulated in maturing photoreceptors and PGK1 deficiency has been implicated in one case of retinitis pigmentosa." (PMID 21527995, 2011).
sarcopenia (2 papers, 2025). Progressive decline in muscle mass due to aging which results in decreased functional capacity of muscles. "Correspondingly, the sarcopenia model showed marked differential expressions of BCL6, DDIT4, FLNA, FOXO1, NFKBIA, PGK1, and STAT3." (PMID 41282482, 2025).
triple-negative breast carcinoma (2 papers, 2021). An invasive breast carcinoma which is negative for expression of estrogen receptor (ER), progesterone receptor (PR), and human epidermal growth factor receptor 2 (HER2). "Furthermore, the expression of PGK1 was determined in Triple-negative breast cancer (TNBC) and found that PGK1 mRNA expression was significantly up-regulated in TNBC patients (p < 0.0001)." (PMID 34291087, 2021).
ankylosing spondylitis (1 paper, 2023). An autoimmune chronic inflammatory disorder characterized by inflammation in the vertebral joints of the spine and sacroiliac joints. "This study intended to assess the role of the lncRNA HOXA transcript at the distal tip (HOTTIP)/miR-30b-3p/phosphoglycerate kinase 1 (PGK1) axis in ankylosing spondylitis (AS)." (PMID 36964567, 2023).
Aortic dissection (1 paper, 2025). Aortic dissection refers to a tear in the intimal layer of the aorta causing a separation between the intima and the medial layers of the aorta. "In addition to PGK1 and HMGA1, several other lactylation-related genes identified in our analysis, such as GAPDH and ALDH1A1, may also contribute to the pathophysiological mechanisms of aortic dissection." (PMID 40596702, 2025).
atherosclerosis (1 paper, 2021). A disease characterized by the build-up of fatty material and calcium deposition in the arterial wall resulting in partial or complete occlusion of the arterial lumen. "The increase of PGK1 can also reduce the formation of atherosclerosis." (PMID 34295249, 2021). "Among them, ANXA2, ApoA1, PGK1, CEBPB and MAP3K3 were related to atherosclerosis and cerebral inflammation." (PMID 34295249, 2021).
cerebral palsy (1 paper, 2024). A group of disorders affecting the development of movement and posture, often accompanied by disturbances of sensation, perception, cognition, and behavior. "Additionally, a next-generation sequencing study in 20 patients with cerebral palsy found that 11 patients (55%) had pathogenic or potentially pathogenic variants, including one patient with a mutation in the PGK1 gene, indicating that a disrupted PPARγ network can lead to abnormalities." (PMID 39065726, 2024).
cholesteatoma (1 paper, 2020). A pathologic process characterized by the proliferation of keratinizing squamous epithelium resulting in the accumulation of keratin and cells in the middle ear and/or mastoid. "However, the differences in expression levels between tissue groups for each gene were small; only the expression of HPRT1, PGK1, PPIA, ATP5B and YWHAZ was significantly higher in healthy MA compared to the mucosa from the middle ear in cholesteatoma patients." (PMID 32915926, 2020).
cognitive decline (1 paper, 2025). "Downregulation of PGK1 may contribute to cognitive decline in female AD patients by increasing Aβ and tau pathology through the suppression of glycolysis and autophagy in the HC." (PMID 41189817, 2025).
colorectal tumor (1 paper, 2024). "Proteins that regulate glycolysis (PGK1, PGAM1, ENO1, PKM, TKT), ammonia detoxification (GLUD1), and other metabolic pathways (LDHA, GAPDH, MDH2) were reported to be differentially expressed in mouse xenograft colorectal tumor models with different radio- responsiveness." (PMID 38410100, 2024).
cyst (1 paper, 2021). A sac-like closed membranous structure that may be empty or contain fluid or amorphous material. "Similarly, another enzyme in carbon metabolism, phosphoglycerate kinase 1, was also more enriched in CS than CWS, which was abundant in T. hydatigena cyst fluid but not in E. granulosus cyst fluid." (PMID 33981740, 2021).
cystic kidney disease (1 paper, 2018). A congenital or acquired kidney disorder characterized by the presence of renal cysts. "GAPDH, PPIA and PGK1 were also recommended as reference transcripts in studies about mice with cystic kidney disease." (PMID 29534701, 2018).
diabetic cardiomyopathy (1 paper, 2025). Diabetic cardiomyopathy is a disorder of the heart muscle in people with diabetes. "Meanwhile, in the field of diabetic cardiomyopathy (DCM), research has found that PGK1 may play a promoting role by driving the polarization of M1 macrophages." (PMID 40496561, 2025).
endometrial tumor (1 paper, 2019). "Using qPCR, we observed markedly higher expression of PGK1 in endometrial tumor tissues (n = 56) compared with normal human endometrial tissues (n = 20)." (PMID 30925862, 2019). "First, we evaluated the expression levels of PGK1 in clinical endometrial tumor tissues." (PMID 30925862, 2019). "We next identified a correlation between the PGK1 expression level and the FIGO stages of the tumor tissues, and found higher expression level of PGK1 in stage III/IV endometrial tumor tissues (n = 37) than in stage I/II endometrial tumor tissues (n = 19)." (PMID 30925862, 2019).
endometrioid carcinoma (1 paper, 2021). "PGK1 showed the highest high positive rate in mucinous carcinoma (100.00%) and the lowest high positive rate in endometrioid carcinoma (68.75%)." (PMID 34277429, 2021). "GLUT1, MCT4, PFKP, PGK1, and PKM2 had lower expression levels in endometrioid carcinoma." (PMID 34277429, 2021).
epilepsy (1 paper, 2025). A brain disorder characterized by episodes of abnormally increased neuronal discharge resulting in transient episodes of sensory or motor neurological dysfunction, or psychic dysfunction. "In addition, the mTOR pathway genes RPS6, TPI1, ENO1, and PGK1 are enriched in PY2-like cortical neurons of brain samples from patients with epilepsy compared with people in a nonepilepsy control group." (PMID 40026248, 2025).
fibrosarcoma (1 paper, 2012). A malignant mesenchymal fibroblastic neoplasm affecting the soft tissue and bone. "PGK1, a phosphoglycerate kinase, is secreted by fibrosarcoma cells at levels several-fold higher than for normal fibroblasts." (PMID 22848707, 2012).
fungal infections (1 paper, 2021). "Although Pgk1 is primarily a glycolytic enzyme localized in the cytoplasm, it is also exposed on the Candida surface and has been identified as a cell-wall-associated moonlight protein that is immunoreactive during invasive fungal infections in humans." (PMID 34200478, 2021).
gastric ulcer (1 paper, 2021). An ulcerated lesion in the mucosal surface of the stomach. "Combining with the empirical results, we supposed alfuzosine, prazosin and terazosin target Pgk1 to enhance glycolysis to block cell death in ulcerative colitis and gastric ulcer." (PMID 35008842, 2021).
glaucoma (1 paper, 2016). Increased pressure in the eyeball due to obstruction of the outflow of aqueous humor. "On the metabolic side, decreased levels of pyruvate kinase, alpha-enolase, triose phosphate isomerase, phosphoglycerate kinase 1, fructose-bisphosphate aldolase A are indicative for a lower glycolytic capacity of glaucoma patients compared to controls." (PMID 27788204, 2016).